SOFU1 (sperm-oocyte fusion factor 1)
Description:
Sperm protein required for fusion of sperm with the egg membrane during fertilization.
Synonyms: LLCFC1; C7orf34; SOF1; CTM-1
Tractability: Antibody: UniProt places it where antibodies can reach, with high confidence; UniProt predicts a signal peptide or a membrane-spanning region; its Gene Ontology location is reachable by antibodies, with medium confidence.
Gene: Protein-coding gene on chromosome 7 (142,939,343 to 142,940,868, forward strand). Ensembl gene ENSG00000165131.
Subcellular location: Secreted
Gene Ontology:
Biological process: fusion of sperm to egg plasma membrane involved in single fertilization
Cellular component: extracellular region
Genetic constraint (gnomAD): Loss-of-function variants: 14 observed, 10.42 expected, observed/expected ratio (o/e) 1.34, 90% interval 0.88 to 1.88. The upper end of that interval is the gene's LOEUF score, 1.88, which puts it in group 6 of 6, group 1 being the genes least tolerant of losing a copy. Missense variants: 162 observed, 154.63 expected, observed/expected ratio (o/e) 1.05, 90% interval 0.92 to 1.19. Synonymous variants: 70 observed, 61.59 expected, observed/expected ratio (o/e) 1.14, 90% interval 0.94 to 1.39.
Homologues: Orthologues: chimpanzee LLCFC1 (99% identical), macaque LLCFC1 (88% identical), pig LLCFC1 (64% identical), dog LLCFC1 (54% identical), rat Llcfc1 (48% identical), mouse Llcfc1 (43% identical).
Diseases named in the same sentence as SOFU1 in open-access papers:
SOFU1 is named in the same sentence as 1 disease in open-access papers, as found by Europe PMC text mining. Sharing a sentence is not in itself a finding about the gene and the disease.
SOFU1 shares sentences with these, for which no sentence is quoted: cancer (1 paper).